FABP5 (fatty acid binding protein 5)
Diseases named in the same sentence as FABP5 in open-access papers (continued):
Sharing a sentence is not in itself a finding about the gene and the disease.
hepatocellular carcinoma (33 papers, 2017 to 2026). A malignant tumor that arises from hepatocytes. "In further, it was found that fatty acid binding protein 5 is up-regulated in hepatocellular carcinoma and associates with poor prognosis." (PMID 39194582, 2024). "In virtually all cancers studied, including hepatocellular carcinoma, gastric and colon cancers, glioma, skin cancer, lung cancer, renal cancer, prostate cancer (PC), and breast cancer, FABP5 expression is associated with increased tumor growth, migration, and/or invasiveness." (PMID 37207357, 2023). "To assess the function of FABP5 in macrophages, we treated macrophages with exosomes derived from FABP5 knockout (KO) or wild-type (WT) hepatocellular carcinoma cells." (PMID 41035647, 2025). "Using ELISA, we also found that MELK knockdown reduced FABP5 secretion by hepatoma cells with CHX exposure time." (PMID 39871325, 2025). "Cellular experiments demonstrated that FABP5 overexpression enhances proliferation, migration, and invasion in hepatocellular carcinoma (Huh7) and gastric cancer (HGC‐27) cell lines, while FABP5 knockdown reduces these effects." (PMID 40178066, 2025). "The molecular mechanism flowchart showed that MELK stabilizes FABP5 to amplify the anti-hepatoma cancer effect of RFA." (PMID 39871325, 2025). "For example, FABP5 is highly expressed and promotes tumor proliferation in hepatocellular carcinoma, but its low expression suppresses tumor progression in colorectal cancer, a mechanism involving mTOR-mediated autophagy activation." (PMID 40717587, 2025). "FABP5 drives obesity-induced hepatocellular carcinoma by promoting lipid peroxidation resistance and immunosuppression, while its inhibition induces ferroptosis and a pro-inflammatory tumor microenvironment, offering a potential therapeutic strategy." (PMID 39315094, 2024). "This phenomenon was suppressed when FABP5 or HIF-1α were silenced, indicating that the FABP5/HIF-1α axis is involved in OA-driven hepatocellular carcinoma cell growth." (PMID 37373069, 2023). "In HepG2 hepatocellular carcinoma cells, OA was found to facilitate survival through the FABP5–hypoxia-inducible factor-1 alpha (HIF-1α) axis, which plays a pivotal role in response to hypoxic stress." (PMID 37373069, 2023). "For the molecular mechanism, FABP5 promoted lipid metabolism reprogramming of hepatocellular carcinoma by enhancing hypoxia-inducible factor-1 alpha activity." (PMID 37124494, 2023). "In hepatocellular carcinoma, the upregulation of FABP5 enhances hypoxia-inducible factor-1 alpha (HIF-1α) activity, causing lipid metabolism reprogramming, and carcinoma progression." (PMID 34934042, 2021). "If FABP8 proves critical in specific cancers, its inhibitors could become novel therapeutic strategies, similar to those explored for FABP5 in hepatocellular carcinoma." (PMID 40717587, 2025). "The combination of FABP5‐targeted nanotherapy, RFA, and anti‐PD‐L1 synergistically suppresses tumor progression and metastasis, highlighting FABP5 as a promising diagnostic marker and therapeutic target in hepatocellular carcinoma." (PMID 40956367, 2025). "For example, FABP4 enhances mitochondrial β-oxidation to reduce cisplatin-induced apoptosis in ovarian cancer, while FABP5 promotes chemoresistance in hepatocellular carcinoma through the HIF-1α pathway, and FABP6 enhances CRC resistance to oxaliplatin through KLF5-dependent transcription." (PMID 40717587, 2025). "In addition, we generated MELK knockout and FABP5 knockout hepatoma cell lines for in-depth investigation." (PMID 39871325, 2025). "For instance, in hepatocellular carcinoma, a lipid-rich microenvironment and hypoxic conditions may favor FABP5-mediated metabolic reprogramming and immune suppression." (PMID 40717587, 2025).
hepatocellular carcinoma (continued). "On the other hand, FABP5 promotes cancer invasion by inducing the epithelial-to-mesenchymal (EMT) transition of hepatocellular carcinoma (HCC), and targeting FABP5 results in altered profiles of lipid signaling intermediates and decreases lipid-mediated invasion in PCa cells." (PMID 40814339, 2025). "Furthermore, FABP5 expression was significantly upregulated in the tumor tissue of the mouse hepatoma model following RFA treatment." (PMID 39871325, 2025). "Up-regulated FABP5 induced by fatty acid actuates hepatocellular carcinoma progress." (PMID 34249967, 2021). "Therefore, we hypothesized that MELK promotes PI3K/Akt/mTOR signaling by enhancing the protein stability of FABP5 in hepatoma cells." (PMID 39871325, 2025). "FABP5 is highly expressed in hepatocellular carcinoma (HCC) and promotes tumor progression through multiple mechanisms." (PMID 40717587, 2025). "It has been reported that increased intra-tumoral FABP5 contributes to CD8+ T-cell infiltration and is linked to overall and recurrence-free survival, indicating that FABP5 could be an immunometabolic marker in hepatocellular carcinoma." (PMID 35370940, 2022). "Herein, we report that FABP5 and HIF-1α were upregulated in hepatocellular carcinoma (HCC) tissues and their expression levels were associated with poor prognosis." (PMID 33128030, 2020). "Recently, it has been shown that in hepatocellular carcinoma (HCC) tissues, FABP5 induced HIF-1α expression and activity, and their expression levels were associated with poor prognosis." (PMID 40016284, 2025). "MELK knockdown and FABP5 overexpression in hepatoma SK-HEP1 and HCC-LM3 cells showed that MELK inhibited the Ub-mediated degradation of FABP5, stabilizing FABP5 protein expression and thereby increasing the phosphorylation of downstream Akt." (PMID 39871325, 2025). "In the hepatocellular carcinoma cell line Huh7 and the gastric cancer cell line HGC‐27, overexpression of FABP5 enhanced cancer cell proliferation, migration, and invasion, whereas knockdown of FABP5 attenuated these capabilities." (PMID 40178066, 2025). "In human hepatocellular carcinoma (HCC) samples, TILs that have enhanced fatty acid-binding protein 5 (FABP5) expression and lipid uptake display stronger effector function and survival." (PMID 37342333, 2023). "In hepatocellular carcinoma (HCC) tissues, both FABP5 and HIF-1α are upregulated, and their expression levels are associated with poor prognosis." (PMID 33128030, 2020). "In hepatocellular carcinoma (HCC), co-amplification of FABP8 with other FABP members (e.g., FABP5) may promote tumor progression by regulating lipid metabolism, although the specific mechanism remains unclear." (PMID 40717587, 2025). "In hepatocellular carcinoma (HCC), FABP9 co-amplifies with other FABP family members (e.g., FABP4, FABP5), which may synergistically promote lipid metabolic reprogramming and tumor progression." (PMID 40717587, 2025). "However, the mechanisms explaining the involvement of FABP5 in hepatocellular carcinoma (HCC) remain unclear." (PMID 35816613, 2022). "FABP5 has been shown to promote angiogenesis by activating the IL6/STAT3/VEGFA pathway and is proposed to be a potential antiangiogenic target for the treatment of hepatocellular carcinoma." (PMID 33352874, 2020). "In hepatocellular carcinoma (HCC), FABP12 forms a gene cluster with FABP4, FABP5, FABP8, and FABP9, which is frequently co-amplified." (PMID 40717587, 2025).
Obesity (31 papers, 2011 to 2025). Accumulation of substantial excess body fat. "Since obesity is a known MM risk factor and FABP5 can regulate diet-induced obesity, we explored the influence of body mass index (BMI) on our findings in the CoMMpass dataset." (PMID 36880649, 2023). "FABP5 as a specific factor that is correlated with lipid metabolism and inflammation, presents a novel and viable idea for understanding obesity-associated inflammatory skin diseases in humans." (PMID 35445019, 2022). "Mice deficient in FABP4 and FABP5 reveal a striking phenotype with strong protection against diet-induced obesity, insulin resistance, type 2 diabetes and fatty liver disease." (PMID 29850615, 2018). "Fabp5 is essential for the pathogenesis of IR associated with obesity and lipid metabolism." (PMID 39075482, 2024). "These suggest that the lipid environment change in the lung tissue caused by HFD administration might reduce the expression of FABP5 and leads to the exacerbation of allergic lung inflammation in obesity." (PMID 33024217, 2020). "Furthermore, HFD-induced obesity causes the downregulation of FABP5 and retinaldehyde dehydrogenases in the lung tissue of mice." (PMID 33024217, 2020). "Mice with combined deficiency of FABP4 and FABP5 (Fabp4−/−Fabp5−/−) on a high-fat diet or in a genetic obesity model exhibit remarkably improved insulin resistance and protection against type 2 diabetes and fatty liver disease more than did FABP4- or FABP5-deficient mice." (PMID 22121495, 2011). "HFD-induced obesity in mice leads to increased FTO levels and loss of m6Am at specific targets such as Fabp2 and Fabp5 mRNAs." (PMID 40862085, 2025). "In particular, both FABP4 and FABP5 have emerged as key contributors to obesity-induced IR: their dual silencing in white adipose tissue significantly reduced inflammation and improved insulin sensitivity in preclinical models." (PMID 41372973, 2025). "Loss of Fabp5 gene expression leads to increased systemic insulin sensitivity in animal models of obesity and IR, and adipocytes isolated from Fabp5 -/- mice also exhibit increased insulin-stimulated glucose transport capacity." (PMID 39075482, 2024). "In animal models, combined deficiency of FABP4 and FABP5 ensures more excellent defence against insulin resistance, obesity, and atherosclerosis than mice deficient for either FABP4 or FABP5." (PMID 34529222, 2022). "This remarkable observation reconfirmed the contribution of FABP5 in the lipid metabolism and development of obesity." (PMID 35445019, 2022). "Consistent with increased circulating lipids and fatty acids in obesity, a 6-month WD induced increased expression of fatty acid and lipid transporters Cd36, Fabp4, Fabp5 and Abca1 in liver ECs, which was partially restored by the reversion diet." (PMID 36400935, 2022). "FABP5 is known to play a role in the onset of obesity by regulating several obesity-related metabolisms." (PMID 33024217, 2020). "Fabp4-/- mice do not weigh less than wildtype mice due to the compensatory upregulation of Fabp5 but they are protected from diet-induced obesity, obesity-induced insulin resistance, and hyperglycaemia." (PMID 31260507, 2019). "In another study, ablation of adipocyte/macrophage lipid chaperones aP2 (FABP4) and mal1 (FABP5) increased adipose DNL which protected mice from diet-induced obesity, fatty liver disease and insulin resistance." (PMID 26752997, 2016). "Here, we discuss the molecular and cellular basis of the roles of FABPs, especially FABP4 and FABP5, in metaflammation and related diseases including obesity, diabetes, and atherosclerosis." (PMID 22121495, 2011). "Deletion of FABP5 resulted in a mild increase in systemic insulin sensitivity in genetic and dietary obesity mouse models." (PMID 22121495, 2011). "Fatty acid binding protein 5 (FABP5) has been identified as a driver of obesity-induced HCC." (PMID 39396974, 2024). "Among fatty acid transporters, Fabp5 showed the strongest obesity-induced upregulation in AT ECs." (PMID 36400935, 2022).
Obesity (continued). "Similarly, obesity triggered increased expression of the liver-specific fatty acid transporter Fabp1 in hepatic cap ECs and of fatty acid transporters Fabp4, Cd36, Fabp5, Dbi and Lpl in art and ven ECs from AT." (PMID 36400935, 2022). "There is a redundant function between FABP4 and FABP5, as Fabp4 and Fabp5 (Fabp4/5 double-knockout (DKO) mice) exhibited a dramatic phenotype related to protection against obesity, insulin resistance, atherosclerosis, and fatty liver disease compared to Fabp4-/- or Fabp5-/- mice." (PMID 36553568, 2022). "FABP5 is up-regulated in macrophages and keratinocytes in skin tissues during a high-fat diet, thereby significantly instigating inflammatory skin lesions in the obesity mouse model." (PMID 35445019, 2022). "In addition, the identification of lean-specific m6Am-methylated key metabolic genes (including Fabp2, and Fabp5) further support m6Am function in the dynamic regulation of obesity." (PMID 34893620, 2021). "In addition, HFD feeding was found to increase mRNA expression of GIP and to induce obesity through the binding of meal-derived free fatty acids to its binding protein, fatty acid binding protein 5 (FABP5)." (PMID 31509948, 2019). "Based on our study, we may only hypothesize that increased expression of FABP5 in obese VAT compared with obese SAT could be due to the fact that VAT is more metabolically active than SAT in obesity." (PMID 29335416, 2018). "In fact, FABP4 and FABP5 have been involved in obesity, atherosclerosis, and metabolic disease." (PMID 30142969, 2018). "Ablation of FABP5 led to a mild increase in systemic insulin sensitivity in genetic and dietary obesity mouse models, whereas adipose tissue-specific overexpression of FABP5 in transgenic mice resulted in a reduction in systemic insulin sensitivity in a high-fat diet model." (PMID 24278421, 2013). "However, additional studies are needed to explain the exact role of FABP5 in human obesity." (PMID 29335416, 2018). "The abundance of different obesity related proteins such as LEP, ITGAL, IKBIP, H2-AA, TAP2 and FABP5 was very low in AdEVs from lean mice and was detected in only one or no biological replicate." (PMID 36759608, 2023). "For example, two obesity-related fatty acid-binding proteins, FABP2 and FABP5, which lost their m6Am under HFD were both significantly downregulated at the protein levels, while Fabp5 also displayed >10-fold downregulation at the mRNA level as well." (PMID 34893620, 2021). "We find that FTO levels are elevated in fat mice, and that genes which lost m6Am marking under obesity are overly downregulated, including the two fatty-acid-binding proteins FABP2, and FABP5." (PMID 34893620, 2021). "In prior studies, FABP5 was highly and exclusively expressed in enteroendocrine K cells, maintaining the normal level of glucose-dependent insulinotropic polypeptide (GIP), which regulates diet-induced obesity in response to fat ingestion." (PMID 39542983, 2024). "We also examined genes correlated with FABP5 and found none ontologically related to obesity, again suggesting that FABP5 effects are BMI-independent." (PMID 36880649, 2023). "Significantly higher levels of FABP5 were observed in both groups of psoriatic patients (with and without obesity) compared to the healthy control subjects." (PMID 34131888, 2021). "Combined with the conclusion of Maeda that the lack of both FABP4 and FABP5 has a stronger protective effect on diet-induced insulin resistance, obesity, and atherosclerosis than any single lack, so we speculated that silibinin may also affect lipid transport through FABP5." (PMID 32184719, 2020).
atherosclerosis (30 papers, 2011 to 2025). A disease characterized by the build-up of fatty material and calcium deposition in the arterial wall resulting in partial or complete occlusion of the arterial lumen. "FABP5 deficiency suppresses the development of insulin resistance, diabetes mellitus and atherosclerosis." (PMID 38653992, 2024). "Studies on cardiometabolic risk suggest an association between FABP5 and the development of obesity-related metabolic syndrome (MetS) and atherosclerosis." (PMID 38596682, 2024). "A previous study has shown that serum Fabp5 concentration is a potential biomarker for residual risk of atherosclerosis." (PMID 38097926, 2023). "Mice with combined deficiency of FABP4 and FABP5 exhibited protection against type 2 diabetes, fatty liver disease and atherosclerosis more than did FABP4- or FABP5-deficient mice." (PMID 33597568, 2021). "Dual ablation of FABP4 and FABP5 was shown to protect from metabolic disorders including insulin resistance, fatty liver, and atherosclerosis more than does a single deficiency of FABP4 or that of FABP5 in mouse models." (PMID 33071982, 2020). "Both FABP4 and FABP5 are secreted from cells, and their circulating levels are associated with insulin resistance and atherosclerosis." (PMID 28303004, 2017). "This assumption is supported by the fact that FABP5 can be overexpressed in adipocytes when a loss of FABP4 occurs and that FABP5 is correlated with the development of atherosclerosis and insulin resistance, too." (PMID 38777142, 2024). "FABP5 inhibits liver macrophage differentiation to the M2 phenotype and plays an important role in the occurrence and development of diabetes and atherosclerosis." (PMID 36426356, 2022). "Experimental studies using FABP5-knockout mice showed the relationship of FABP5 with insulin resistance and atherosclerosis." (PMID 33071982, 2020). "Compared to mice with a single deficiency of FABP4 or FABP5, the combined deficiency of FABP4 and FABP5 better improves insulin sensitivity and protects against atherosclerosis and type II diabetes." (PMID 30142969, 2018). "Fatty acid-binding protein 4 (FABP4) and FABP5 are expressed in both adipocytes and macrophages and play significant roles in the development of insulin resistance and atherosclerosis." (PMID 28303004, 2017). "In conclusion, in contrast to FABP4, circulating FABP5 is associated with decreased CEC and carotid atherosclerosis, suggesting that FABP5 level is a regulatory factor of CEC and a potential biomarker for residual risk of atherosclerosis." (PMID 28303004, 2017). "Mice that are knockout for both the adipocyte and epidermal fatty acid-binding protein (FABP4 and FABP5, respectively) are protected against the metabolic syndrome and atherosclerosis." (PMID 23349676, 2013). "It has been demonstrated that both FABP4 and FABP5 play important roles in the regulation of insulin sensitivity and the development of atherosclerosis and that their impacts differentially involve adipocytes or macrophages." (PMID 22121495, 2011). "Taken together with the consensus that FABP5 plays significant roles in several aspects of metabolic syndrome, including hypertension and atherosclerosis, there may be some FABP5-dependent interplay between levels of IOP and hypertension." (PMID 40076418, 2025). "In addition, prior studies reported that the expression of FABP5 in the plasma of patients with femoral atherosclerosis was increased, and the expression of FABP5 in atherosclerotic plaque tissue was significantly higher than that in normal intima tissues." (PMID 38068935, 2023). "Interestingly, the impact of FABP5 on reduction of atherosclerosis was even greater than that of FABP4." (PMID 28303004, 2017). "However, little is known about the link between CEC and levels of FABP4 and FABP5 regarding the development of atherosclerosis." (PMID 28303004, 2017).